IL17A (interleukin 17A)
Diseases named in the same sentence as IL17A in open-access papers (continued):
Sharing a sentence is not in itself a finding about the gene and the disease.
prostate carcinoma (110 papers, 2014 to 2025). A carcinoma that arises from epithelial cells of the prostate gland. "The peripheral blood cytokines are closely associated with the occurrence and development of prostate cancer, especially the serum levels of IL-6 and IL-17A may be useful as potential predictors of PCa diagnosis." (PMID 38833027, 2024). "The findings of this study suggest that IL-17A and IL-17RA may be useful in predicting the risk of aggressive prostate cancer; however, further studies are needed to determine their roles and potential clinical applications." (PMID 37760548, 2023). "The expression of IL-17A cytokine and its receptor IL-17RA may be used to predict the risk of aggressive prostate cancer." (PMID 37760548, 2023). "The area under the curve (AUC) of IL-6 and IL-17A in the diagnosis of prostate cancer patients were 0.721, and 0.710, respectively, demonstrates “good” capability for discriminating between patients with PCa and controls." (PMID 38833027, 2024). "A recent report suggested that IL‐17A promotes prostate cancer via MMP7‐induced EMT, which further supports the regulation of EMT by IL‐17A." (PMID 29689643, 2018). "IL-17A also promotes development of colon cancer, skin cancer, breast cancer, prostate cancer, lung cancer, and pancreas cancer." (PMID 26871944, 2016). "IL-17 A is the vital cytokine secreted by Th17 cells, and several studies have further confirmed that Th17-IL-17 pathway could play an important role in development of primary prostate cancer and lymph node metastasis." (PMID 40055805, 2025). "Furthermore, a generalized linear mixed model identified statistically significant associations between prostate cancer risk and SNPs in IL12RB2, IL13, IL17A, IL4R, MAPT, and TFNRS1B." (PMID 37108754, 2023). "As earlier studies show, IL-17A expression increased in more than 50% of prostate cancers." (PMID 36012113, 2022). "Our former research results show that IL-17A and IL-17 F contribute to the pathogenesis of benign prostatic hyperplasia (BPH) and prostate cancer (Pca) while IL-17E interacting with IL-17RB might have an anti-tumor effect." (PMID 27716046, 2016).
osteoarthritis (108 papers, 2005 to 2025). A noninflammatory degenerative joint disease occurring chiefly in older persons, characterized by degeneration of the articular cartilage, hypertrophy of bone at the margins and changes in the synovial membrane. "As for IL-17A(rs2275913), it is believed that allele A can promote the high expression of IL-17A, which may be a risk factor for the occurrence of osteoarthritis." (PMID 31842922, 2019). "Increased interleukin (IL)-17A has been identified in joints affected by osteoarthritis (OA), but it is unclear how IL-17A, and its family members IL-17AF and IL-17F, can contribute to human OA pathophysiology." (PMID 34054865, 2021). "We investigated the presence of IL‐17A and IL‐17F protein in paired serum and SF from patients with IA, and in serum from healthy controls and serum and SF from osteoarthritis patients as controls." (PMID 31850514, 2020). "More studies of the role of IL-17A in diseases such as osteoarthritis, where cartilage damage is at the center of the pathophysiology, remain to be undertaken." (PMID 31485194, 2019). "A potential clinical effect of IL-17A blocking therapies in osteoarthritis will also be an interesting topic to explore." (PMID 31485194, 2019). "RA synovial explants spontaneously produce IL-17A, and increased levels of IL- 17A are found in RA synovial fluid compared with osteoarthritis synovial fluid." (PMID 23308194, 2013). "IL-17A has also been detected in SF from osteoarthritis (OA) patients; however, levels were lower than in RA SF." (PMID 19627579, 2009). "IL-17A levels were higher in RA vs osteoarthritis (OA)/normal joints (P < 0.05)." (PMID 19627579, 2009). "This includes lutikizumab (anti-IL1a and IL1b) for osteoarthritis, and COVA322, a bispecific TNF/IL17A antibody fusion protein studied in phase 1/2 in patients with stable chronic moderate-to-severe plaque Pso (stopped for safety reasons)." (PMID 40529150, 2025). "In addition, in osteoarthritis, low expression of MIR4435-2HG can attenuate the MIR4435-2HG/miR-510-3p/IL-17A axis signal and activate the NF-κB signaling pathway, thereby mediating the process of osteoarthritis." (PMID 35784328, 2022). "The PI3K/AKT signaling pathway is an inflammatory pathway that may be mediated by TNF-α in osteoarthritis, and TNF-α inhibitor treatment significantly reduced the expression of IL-1, IL17a, and IL8 in synovial fibroblasts." (PMID 35046814, 2021). "In line with previous studies 23, 27, IL‐17A protein was detected at increased concentrations in the SF versus serum of IA patients, while no IL‐17A protein was detectable in healthy control serum or paired serum or SF from patients with osteoarthritis." (PMID 31850514, 2020). "Additionally, IL-17A levels have been reportedly higher in patients living with osteoarthritis, relative to those without a pain condition." (PMID 40649738, 2025). "Third, regardless of the fact that IL-17A and IL-17F can mediate cartilage degeneration, it may not be a direct determinant of osteoarthritis." (PMID 31842922, 2019).
fibrosis (96 papers, 2011 to 2025). the formation of excess fibrous connective tissue in an organ or tissue in a reparative or reactive process. "IL-17A is one of the cytokines produced by the Th17 cells and has been implicated in the pathogenesis of a number of disease conditions including the Schistosoma associated fibrosis." (PMID 29610679, 2018). "Interleukin-17 is therefore implicated in the pathology of pneumonitis as well as in fibrosis, a finding which is supported by one report wherein anti Il17a monoclonal antibody treatment was shown to prolong the survival of whole thorax irradiated C57BL/6J mice." (PMID 28912510, 2017). "Plasma IL-10/IL-17A ratio and IL-10/IL-22 ratio significantly differed between F0 fibrosis vs. moderate (F2)." (PMID 40918132, 2025). "Using murine SSc models, it was reported that IL-17A/TH17 cells can promote fibrosis of the skin and lungs by stimulating the progression and secretion of type 1 collagen." (PMID 38674328, 2024). "Analysis of IL-17A and associated cytokine expression by immune cells extracted from human liver and stimulated in vitro by mitogens for one week, previously, showed a direct correlation of IL-17A and IL-22 secretion with fibrosis stage." (PMID 36077175, 2022). "Anti-IL-17A antibodies have been reported to inhibit intestinal fibrosis development through repressing EMT." (PMID 35002710, 2021). "Interleukin-17A contributes to the development of AF by promoting inflammation and cardiac fibrosis and affecting protein kinase C (PKC)-β and Erk 1/2 phosphorylation, as well as nuclear factor (NF)-κB activation in fibroblasts from model mice." (PMID 34721413, 2021). "H&E and Masson staining showed that PM2.5-induced pulmonary injury and fibrosis were attenuated when IL-17a was deleted in mice." (PMID 32554855, 2020). "We found a direct influence of IL-17A on oxidative stress formation, vascular fibrosis, and the ·NO/cGMP signaling resulting in severe vascular dysfunction without direct vascular immune cell infiltration." (PMID 31396305, 2019). "The frequency of IL-17A and IL-17F distinguish SSc to morphea individuals while dermal expression of IL-17C (low) and IL-17E (high) identifies a fibrosis-specific motif." (PMID 25136988, 2014). "Recent data from bleomycin-induced lung injury demonstrated an early IL-17A mediated pulmonary inflammation leading to fibrosis." (PMID 23936171, 2013). "Our findings demonstrate the existence of an early IL-1β-IL-23-IL-17A axis leading to pulmonary inflammation and fibrosis and identify innate IL-23 and IL-17A as interesting drug targets for IL-1β driven lung pathology." (PMID 21858022, 2011). "In this study, we report the involvement of IL-23p19 and innate IL-17A in the occurrence of pulmonary inflammation and fibrosis and demonstrate the critical role of IL-1β in these processes." (PMID 21858022, 2011). "Effects of depletion of Tregs by anti-CD25 administration, and of administration of anti-IFN-γ, anti-IL-17A or anti-IL-17F on fibrosis after three cycles of DSS, were evaluated first by quantification of collagen deposition in mucosa and submucosa by MSB trichrome staining." (PMID 31296924, 2019). "In conclusion, in this study, we clearly demonstrate the significant increase in the expression of IL-17A in rats with SP, which may contribute to the development of AF by stimulating inflammatory responses and promoting cardiac fibrosis." (PMID 25955429, 2015). "Blocking IL-17A facilitates the resolution of pulmonary inflammation and fibrosis." (PMID 22808256, 2012). "Anti-IL-17A mAb treatment during this period of infection reduced immune cell infiltration at early stages of infection (2 and 4 weeks postinfection) and reduced lung fibrosis, bacterial burden and mortality at chronic stages of infection (after 39 weeks of infection)." (PMID 35363832, 2022). "Neutralizing the IL-17A antibody reduced inflammatory cells in the BAL and ameliorated both granulomatosis and fibrosis in mice with sarcoidosis." (PMID 40724901, 2025).
fibrosis (continued). "Among these genes the most expressed canonical pathways were TREM1 signaling, hepatic fibrosis/hepatic stellate cell activation, ILK signaling, IL-17A signaling in airways cells, and production of nitric oxide and reactive oxygen species in macrophages." (PMID 26649052, 2016). "In this context, treatment with an antibody against IL-17A reduced IL-17A, TGF-β, and IL-6 concentrations and alleviated radiation-induced pneumonitis and subsequent fibrosis in mice." (PMID 28018357, 2016). "Furthermore, IL-17a and the mRNA expression levels of IL-6, TNF-α and TGF-β1 were decreased in the liver tissues of the IDO1–/– fibrosis mice compared with the WT fibrosis mice." (PMID 28465467, 2017). "Similarly, in a model of angiotensin II-induced myocardial injury, treatment with anti-IL-17A antibodies did not reduce myocardial hypertrophy or fibrosis." (PMID 39502194, 2024). "While the exact role of C5b9 in PR8 infection remains poorly understood, a study showed that in a model bleomycin-induced fibrosis, mice lacking interleukin-17 (IL-17A) developed less severe fibrosis, and this was concomitant with a reduction in C5b9 deposition." (PMID 36845136, 2023). "Similar results were observed at the protein level, where IL17A protein was almost absent in normal and paraffin oil control groups of liver tissue while the tissue derived from CCl4-induced fibrosis group and recovery group showed high degree of expression of IL-17A and IL17RA proteins." (PMID 30346985, 2018). "HCV-specific IL-21/ IL-17A responses did not correlate with microbial translocation or fibrosis." (PMID 27124305, 2016). "Taken together, our results show that multicytokine-producing CD4+ T cells, mainly characterized by the expression of IL-17A, are particularly enriched in the liver of those NASH patients with fibrosis compared with those without fibrosis." (PMID 36625344, 2023). "The SNPs in IL17A (rs2275913), IL10 (rs1800871 and rs1800872), and CD209 (rs2287886 and rs4804803) genes were genotyped in the no fibrosis patients (classified as Niamey 1) (n = 28) and fibrosis patients (classified as Niamey 7) (n = 9)." (PMID 34970264, 2021). "During CHC treatment, patients with SLD had distinct cytokine and growth factor kinetics, with SLD being the main source of variation in several cytokines (IL-5, IL-9, IL-10, IL-13, IL-17A, IL-22) and growth factors (EGF, VEGF and ANG), and it seems this was independent of fibrosis stage." (PMID 39200991, 2024). "Among the different multicytokine-producing CD4+ T cells, we discovered that CD4+ T cells producing mainly IL-17A, but not exclusively — i.e., CD4+ T cells with a Th17 polarization state — were significantly enriched in the liver of NASH patients with fibrosis compared with no fibrosis." (PMID 36625344, 2023).
type 1 diabetes (96 papers, 2008 to 2026). "IL-17A/F, together with IL-17A and IL-17F, has been linked to beta cell pathogenesis in type 1 diabetes and multiple autoimmune diseases through activation of the IL-1 receptor agonist." (PMID 39078488, 2024). "Together these data indicate that IL-17F possesses similar pathogenic activities to IL-17A in mouse β-cell lines and islets and is likely to be a type 17 associated pathogenic factor in type 1 diabetes." (PMID 32753746, 2020). "Type 17 immune responses, typified by the production of the cytokines IL-17A and IL-17F, have been implicated in the development of type 1 diabetes in animal models and human patients, however the underlying pathogenic mechanisms have not been clearly elucidated." (PMID 32753746, 2020). "Thus we speculate that IL-17F deficient or IL-17F/IL-17A doubly deficient NOD mice may exhibit more protection from type 1 diabetes than IL-17A deficient NOD." (PMID 32753746, 2020). "IL-17A is an inflammatory cytokine that mediates the severity of multiple autoimmune and inflammatory diseases, including Type I diabetes." (PMID 36674854, 2023). "Previously, we and others have found that IL-17A production is induced in multiple Type I diabetes murine models." (PMID 36674854, 2023). "First, we provide evidence that IL-17A plays a similar pathologic role in Type II diabetes-induced diabetic retinopathy as previously identified in Type I diabetes." (PMID 36674854, 2023). "In non-obese diabetic (NOD) mice, SR1001 treatment prevented Th17 cell differentiation and IL-17A production, which halted Type I diabetes progression and insulitis." (PMID 32429598, 2020). "These Th17 cells release IL-17A and IL-22 and induce type 1 diabetes in young NOD mice upon adoptive transfer." (PMID 31963845, 2020). "In conclusion, no changes in γδ T cells, iNKT cells and NK cells were observed in children with newly diagnosed type 1 diabetes, with the exception of an increased production of IL-17A by γδ T cells." (PMID 32880687, 2020). "No changes in the cytokine production patterns of γδ T cells and iNKT cells were observed, except for an increased frequency of IL-17A+ γδ T cells in children with type 1 diabetes." (PMID 32880687, 2020). "To extend our research in this area, we looked at the potential relationship between the concentration of analyzed cytokines, the level of serum 17β-estradiol, and the frequency of CD4+IL17A+ Th17 cells in girls with type 1 diabetes." (PMID 24523574, 2014). "The study identified that IL-17A/F was a type 1 diabetes-specific temporal biomarker." (PMID 41224288, 2025). "Initial studies indicate increased secretion of IL-17A from activated peripheral blood T cells in children with type 1 diabetes (T1D) and a disorder in IL-17A that may have a significant impact on the course of autoimmune diabetes." (PMID 34750361, 2021). "Moreover, in the same study administration of low dose of recombinant IL-17A or IL-17F reduced albuminuria and renal injury in Ins2 Akita mice, a model for type 1 diabetes." (PMID 31963845, 2020). "In contrast to IL-17A, the role of IL-17F in type 1 diabetes pathogenesis is largely unstudied." (PMID 32753746, 2020). "Firstly that IL-17F and IL-17A could be functionally redundant in type 1 diabetes and that both genes must be inactivated or inhibited for any potential type 1 diabetes protection to eventuate." (PMID 32753746, 2020). "Finally, the results obtained by analyzing the effects of ISA-2011B on CD28-mediated upregulation of inflammatory IL-8, IL-6, and IL-17A genes in T lymphocytes from type 1 diabetes (T1D) patients suggest ISA-2011B as a promising anti-inflammatory drug." (PMID 28491063, 2017). "Moreover, production of Th9 (IL-9) and Th17 (IL-17A) cytokines by T cells from control subjects and type 1 diabetes donors were reduced after exposure to 1,25(OH)2D3 or TX527." (PMID 25279717, 2014).
type 1 diabetes (continued). "We found a higher concentration of IFN-γ, TNF-α, and IL-17A in vehicle-treated T cell cultures from donors with type 1 diabetes than in those from control donors, suggesting more cytotoxic T cells, Th1 and Th17 cells, in line with the inflammation associated with type 1 diabetes." (PMID 25279717, 2014). "Therefore, our current observation may warrant further investigation on the role of IL-17A-producing γδ T cells in human type 1 diabetes." (PMID 32880687, 2020). "Thus type 17 immune responses can be pathogenic in type 1 diabetes, however it is likely that IL-17A is not solely responsible for this pathogenicity." (PMID 32753746, 2020). "Similarly, interventions that block IL-17F and IL-17A simultaneously may have improved therapeutic utility in type 1 diabetes compared to interventions that block either cytokine alone." (PMID 32753746, 2020). "Alternatively IL-17F may have a more important role in type 1 diabetes pathogenesis than IL-17A." (PMID 32753746, 2020). "In type 1 diabetes, MAIT cells show dual roles in maintaining gut barrier integrity by secreting IL-17A and IL-22 but promote β-cell death in the pancreas." (PMID 35317168, 2022). "In NOD mice, serum IL-17A levels and the number of pancreatic IL-17A producing Th17 cells and IFN-γ producing Th1 cells increased, thus identifying a mechanism by which Th17 cells can contribute to type 1 diabetes." (PMID 31963845, 2020). "The SNP rs12416605, located in human type 1 diabetes IDDM10 locus, changes the seeding sequence (UGU[G/A]CCC) of miRNA miR-938 and potentially alters miR-938 targets, including IL-16 and IL-17A." (PMID 22014115, 2011). "However, for the individuals with non-childhood-onset type 1 diabetes (7%), we found a largely similar inflammatory profile, except for a type 1 diabetes-specific increase in IL-17A/F." (PMID 39078488, 2024). "Hence, it was the aim of this study to determine if IL-17A induces non-proliferative diabetic retinopathy in Type II diabetic mice, as identified for Type I diabetes." (PMID 36674854, 2023). "However, IL-17A+ γδ T cells but not iNKT cells were more abundant in children with newly diagnosed type 1 diabetes compared with control children (median 1.58% vs 1.09% of γδ T cells, p = 0.002)." (PMID 32880687, 2020). "In a different setting, using the nonobese diabetes (NOD) animal model for Type 1 diabetes, disease is inhibited following treatment with anti-IL-17A antibodies during the effector phase of disease (at 10 weeks of age) rather than during the initiation of disease (mice less than 5 weeks of age)." (PMID 22229105, 2012). "Furthermore, elevated serum IL-17A and increased islet antigen-specific IL-17A-producing CD4+ T helper (Th17) cells are detected in patients with type 1 diabetes (T1D) while adoptive transfer of Th17 cells into non-obese diabetic (NOD) mice promotes pancreatic inflammation." (PMID 34122457, 2021).
hepatitis B (93 papers, 2011 to 2026). "Research regarding hepatitis B virus infection in kidney transplant and bone marrow recipients revealed that the A allele of the rs2275913 IL17A gene polymorphism was implicated in AR and graft-versus-host disease." (PMID 30961540, 2019). "While biologics are traditionally contraindicated in patients with malignancies and hepatitis B, emerging evidence supports the safety of IL-17A inhibitors in these populations." (PMID 41142781, 2025). "Therefore, slightly elevated IL-17A might exert a synergistic anti-viral effect during acute hepatitis B, while sustained high levels of IL-17A in chronic hepatitis B might involve in HBV persistence and disease progression." (PMID 35144643, 2022).